LMNA (lamin A/C)
Diseases named in the same sentence as LMNA in open-access papers (continued):
Sharing a sentence is not in itself a finding about the gene and the disease.
progeria (continued). "In progeria, a devastating early aging disease, a silent mutation in LMNA causes permanent farnesylation, preventing proteolytic cleavage causing progerin, a misfolded form of lamin A, to build up at the nuclear periphery." (PMID 34455929, 2021). "Hutchinson-Gilford progeria syndrome or progeria is a disease leading to premature aging due to a mutation in the Lamin A (LMNA) gene, resulting in aberrant accumulation of a truncated form of LMNA protein, otherwise known as progerin." (PMID 34516892, 2021). "HGPS (also termed progeria) is a rare genetic disorder (estimated prevalence of 1 in 18–20 million people) caused by a mutation in the LMNA gene that provokes accelerated aging and premature death." (PMID 34064612, 2021). "Progeria is an ultra-rare (prevalence 1 in 20 million), fatal, pediatric autosomal dominant premature aging disease caused by a mutation in the LMNA gene." (PMID 33735109, 2021). "“Classical” progeria is caused by a heterozygous de novo c.1824C>T (p.G608G) point mutation in the LMNA gene." (PMID 34064612, 2021). "A 33-year-old woman was diagnosed with generalized lipodystrophy and atypical progeroid syndrome due to the newly identified heterozygous LMNA p.(Asp136Val) variant." (PMID 32245113, 2020). "LMNA mutations are the second most common genetic cause of progeroid syndromes after WRN mutations in our Registry." (PMID 32954377, 2020). "On the other hand, mutations in the gene for lamin A/C (LMNA), a nuclear membrane protein known to cause skeletal disorders, progeria, muscular dystrophy, and DCM, are also associated with an increased risk for the development of different types of cancer." (PMID 32498335, 2020). "These diseases are caused by LMNA mutations and feature altered bone turnover, metabolic dysregulation, and mild to severe segmental progeria." (PMID 30781376, 2019). "HGPS is one of several progeroid syndromes caused by mutations in the LMNA gene encoding the nuclear structural proteins lamins A and C. In classic HGPS the mutation G608G leads to the formation of a toxic lamin A protein called progerin." (PMID 29907918, 2018). "Apart from progeroid syndromes mutations in the lamin A encoding gene LMNA cause several tissue specific diseases (including muscular dystrophy, neuropathy and lipodystrophy)." (PMID 30140252, 2018). "In particular, LMNA mutations associated with progeroid syndromes and causing accumulation of prelamin A forms increase the rate of osteoclastogenesis and osteolytic activity, while favouring osteoblast differentiation." (PMID 29854317, 2018). "Progeria is caused by a mutation in the LMNA gene, encoding the nuclear proteins Lamin-A/C,43 which results in the accumulation of a truncated form of pre-lamin A termed progerin." (PMID 29514202, 2018). "We report a young patient who carried a rare missense mutation in the LMNA gene and presented with the phenotype that resembled the progeroid syndromes." (PMID 29047356, 2017). "Mutations involving codon 300 in the LMNA gene have been associated with progeroid syndromes involving multiple organs." (PMID 29047356, 2017). "Much less commonly, LMNA mutations cause progeroid syndromes, whereby an early-onset coronary artery disease (CAD) is the hallmark of the disease." (PMID 29047356, 2017). "Recently, the interest in lamins has been remarkably fostered, especially after discovering that mutations in LMNA gene cause the onset of severe diseases like progeria and muscular dystrophies." (PMID 28994747, 2017). "In the heart, LMNA mutations cause two distinct sets of phenotypes, involving primarily either the myocardium or the coronary arteries, the latter in the context of progeroid syndromes." (PMID 29047356, 2017). "In cells from a patient with atypical progeria, carrying a rare point missense mutation p.S143F (C428T) in the LMNA gene, blebs enriched in A-type Lamins but devoid of the major structural NE components have been observed." (PMID 27602048, 2016).
progeria (continued). "Progeria is a rare disease in which LMNA mutations induce cellular and organismal senescence in part by altering stoichiometry and interactions of type A and B Lamins." (PMID 24876127, 2014). "A mouse model of progeria derived by insertion of the human mutant LMNA gene (mLMNA), producing mutant lamin A, shows loss of smooth muscle cells in the media of the ascending aorta." (PMID 24661531, 2014). "The same homozygous mutation of c.1579C > T of LMNA gene led to MADA associated progeria for the present family." (PMID 25286833, 2014). "Severe forms of progeria also occur due to a number of other mutations in LMNA, such as 1821 G > A and 1,968 G > A, mutations associated with increased ratios of progerin to normal, wild-type protein." (PMID 23090008, 2012). "For instance, a type of progeria known as Hutchinson Gilford Progeria Syndrome (HGPS) has been associated with mutations in the lamin A/C gene." (PMID 21547077, 2011). "Interest in the LMNA gene and in NL-associated proteins has grown dramatically since a number of mutations in the LMNA gene were shown to cause a wide range of connective tissue, neuropathological, and premature aging (progeria) syndromes in human patients." (PMID 20376364, 2010). "Mutations in the LMNA gene result in degenerative disorders, including progeria." (PMID 41271669, 2025). "Here the authors show that the most common progeria-causing mutation, LMNA c.1824C>T, is a somatic mutation in arteries from patients with chronic kidney disease, and that clonal propagation of the mutation in the vascular wall results in vascular aging phenotypes in mice." (PMID 40495018, 2025). "Notably, the most common progeria-causing mutation, LMNA c.1824C>T, was identified as a somatic mutation in CKD arteries." (PMID 40495018, 2025). "By identifying that LMNA mutations related to progeria lead to the deletion of this protease site, it has allowed the advances in our understanding of the development of the disease, which has in turn lead to the identification of potential therapeutic candidates." (PMID 36552829, 2022). "Our results obtained in cultured LmnaG609G/G609G osteoblasts confirmed the aberrantly increased differentiation rate of laminopathic osteoblasts previously demonstrated in bone progenitor cells carrying the human progeria G608G LMNA mutation and Mandibuloacral dysplasia osteoblasts." (PMID 33393189, 2021). "LMNA pathogenic variants cause several different laminopathies including muscular dystrophy, cardiomyopathy, neuropathy, lipodystrophy, and syndromes of accelerated aging (progeria and progeroid syndromes)." (PMID 35046902, 2021). "Nevertheless, this effect might be limited to the progeria-causing LMNA mutations since other LMNA mutations seem to induce cognitive decline or white matter lesions of the brain." (PMID 30781626, 2019). "In addition to the LMNA gene, several genes involved in DNA metabolism have been implicated in progeroid syndromes." (PMID 29635765, 2018). "Mutations of LMNA gene encoding lamin A/C are associated with a premature aging syndrome (Hutchinson–Gilford syndrome or progeria) that is generally presented with the subcutaneous tissue loss, leg ulceration, joint abnormalities, coronary atherosclerosis and alopecia." (PMID 29760951, 2018). "In addition to these progeroid disorders there are several cases of so called atypical progeroid syndromes caused by LMNA mutations." (PMID 30140252, 2018). "Therefore, we generated plasmids containing 3XFLAG-tagged human LMNA cDNA with a subset of point mutations found in progeria and congenital muscular dystrophy." (PMID 26900797, 2016). "Direct evidence for tissue specific function of Lamin proteins comes from mutations in the human Lamin A (LMNA) gene, which lead to an array of serious diseases called laminopathies, including cardiomyopathy, muscular dystrophy, lipodystropy, neuropathy and progeria." (PMID 25852741, 2015).
progeria (continued). "LMNA, in addition to multiple myopathic phenotypes, also causes Charcot-Marie Tooth disease or progeria, and SYNE1 can cause one type of Emery-Dreifuss muscular dystrophy, a dilated cardiomyopathy syndrome, a form of autosomal recessive arthrogryposis, and autosomal recessive spinocerebellar ataxia." (PMID 25353622, 2014). "The aim of this study was to look for candidate genes and gene ontology functions influenced by LMNA mutations that in turn may have a role in progeria development." (PMID 23317481, 2013). "The aim of this study was to search for candidate genes and gene ontology functions possibly influenced by LMNA mutations that may exert a role in progeria development." (PMID 23317481, 2013). "Our data do not support the hypothesis that premature CAD is associated with common variants in the progeroid syndrome genes LMNA and KLOTHO." (PMID 16262891, 2005). "Mutational analysis by direct Sanger sequencing of the LMNA gene (NM_170707.4), highlighted a heterozygous likely pathogenetic mutation c.1733A>T (p.Glu578Val) described elsewhere, confirming the clinical presentation of a progeroid syndrome, specifically atypical Werner’s syndrome." (PMID 39769130, 2024). "Our current results verified a crucial role of mtDNA release and mitophagy dysfunction-mediated innate immune activation in mediating LMNA mutation-induced progeria phenotypes, which may help identifying a novel set of diagnostic markers and therapeutic targets for progeria aging." (PMID 39039044, 2024). "On the other hand, the functions of the second rod domain of LMNA are unclear, and the effects of mutations in this region in respect to laminopathic disorders are not well characterized, although such mutations, such as D300G, have more severe effects on progeria." (PMID 36225129, 2022). "Interestingly, the majority of premature aging diseases such as the Hutchinson–Gilford progeria syndrome aka progeria ensue from single point mutations within the LMNA gene that give rise to a permanently farnesylated mutant Lamin A protein, which is termed progerin." (PMID 34298904, 2021). "LMNA mutation in HGPS disease causes increased nuclear stiffness and nuclear abnormalities in the progeria cells; however, the potential regulatory mechanism of nuclear abnormalities in response to mechanical stress remained unclear." (PMID 37198162, 2023). "HGPS as well as APS and MADA are caused by mutations in the LMNA gene that together with MADB, RD, and NGPS belong to a group of progeroid syndromes associated with defects in nuclear organization and stability." (PMID 38481648, 2023). "The discovery of the LMNA gene as a cause of HGPS and progeroid syndromes raised interest in the role of the LMNA protein in aging in the general population." (PMID 35531366, 2022). "Mutations in human Lamin genes (LMNA, LMNB1, LMNB2) lead to a wide-range of diseases including muscular dystrophy, peripheral neuropathy and progeria." (PMID 31225490, 2018). "We also detected the tendency for up-regulation of lamin A (LMNA), which is a gene contributing to progeria and aging." (PMID 25977295, 2015). "The aim of this article was to investigate the network of interactions of LMNA gene to find candidate genes and gene ontology functions involved in Lamin-A functions and in turn possibly perturbed in progeria." (PMID 23317481, 2013). "A point mutation (c.1824 C > T; p.G608G) in the Lamin A (LMNA) gene, leading to a mis-splicing event that results in the loss of 50 amino acids from the Lamin A protein, which is characterized by Hutchinson–Gilford progeria syndrome (HGPS or progeria)." (PMID 37946200, 2023). "The mutation did not manifest with myopathy, lipodystrophy, progeria, or hereditary neuropathy, common manifestations of LMNA variants." (PMID 37303410, 2023).
progeria (continued). "Progeroid syndromes caused by mutations in LMNA, which encodes prelamin A as well as lamin C, and ZMPSTE24, which encodes the prelamin A processing enzyme, the zinc metalloprotease ZMPSTE24, have implicated unprocessed, farnesylated prelamin A or its variants in accelerated aging processes." (PMID 37885131, 2023). "Mutation of LMNA as a cause of several premature aging disorders has long been known, although the molecular mechanisms underlining the link between mutant LMNA and progeria are not clear." (PMID 36225129, 2022). "The role of the LMNA gene in premature aging syndromes is further supported by the identification of additional rare pathogenic variants (PVs) in patients with HGPS and other forms of progeroid syndromes." (PMID 35531366, 2022). "In addition to skeletal muscles, the cardiac muscle, fat and bone defects, LMNA-KO rabbits exhibited detectable pathological changes in the liver, kidney, lung, stomach, lens, cornea and retina, which are proficient in the progeria patient." (PMID 30705772, 2019). "Consistent with the results described in both progeria patients and mice with mutations in the LMNA gene, LMNA-KO rabbits were indistinguishable from WT littermates at birth." (PMID 30705772, 2019). "In addition, when compared to WT controls, LMNA-KO rabbits exhibited decreased eccrine in skin, which is similar to the skin abnormalities reported in the progeria patients." (PMID 30705772, 2019). "The most intriguing examples are LMNA and WRN: while specific variants of these two genes determine progeria and accelerated aging, alternative variants may increase life span." (PMID 22279548, 2012). "This is in line with studies in human, where a large number of mutations of Lamin A/C (LMNA) were found, causing a wide range of human disorders, including lipodystrophy, neuropathies, autosomal dominant Emery-Dreifuss muscular dystrophy (EDMD), and progeria." (PMID 22761545, 2012). "In addition, we find that Lamin Dm0, a Drosophila homologue of the Hutchinson‐Gilford progeria protein, Lamin A/C, is a target for p38Kb and stv mediated protein turnover, suggesting that the p38Kb aging phenotypes may be a result of impaired Lamin degradation." (PMID 34674371, 2021). "Importantly, the accelerated aging syndrome (progeria) gene, HGPS gene (LMNA), is also included in this group related to the structure of the nuclear envelope and pores." (PMID 39408822, 2024). "Lessel et al21 tested 50 patients with a putative diagnosis of nonclassical WS (ie, progeroid syndrome without WRN, LMNA, BANF1, and ZMPSTE24 mutations) and found causative POLD1 mutations in 8 patients." (PMID 30023403, 2018). "In addition to this, known genes involved in segmental progeroid syndromes are also dysregulated, including ATM and LMNA." (PMID 26176221, 2015). "As for the LMNA function in our zebrafish progeria model, it should be noted that the decrease-of-function of LMNA showed specific developmental defects without any significant induction of SA-β-gal i.e. embryonic senescence." (PMID 21479207, 2011). "Therefore, LMNA mutation and WRN deficiency does not facilitate EC senescence, suggesting that the premature aging caused by progeria-associated mutations are cell-type-specific." (PMID 29476423, 2018).
lipodystrophy (82 papers, 2009 to 2025). "There are several clinical presentations of laminopathies, as different LMNA mutations are responsible for different phenotypes, including lipodystrophy, skeletal muscle dystrophy, and cardiomyopathy." (PMID 39470804, 2025). "We cannot exclude that the same phenomenon contributes to the phenotype in pregnancy, at least in patients with lipodystrophy due to LMNA mutations, although tailored studies are needed." (PMID 39479521, 2024). "This study provides the discovery of a novel, monoallelic, de novo variant in the LMNA gene as causative of intellectual disability, lipodystrophy, cardiac symptoms, skin atrophy, cataract, and diabetes mellitus in the proband of family E-3." (PMID 39767643, 2024). "We show that FPLD2/Dunnigan syndrome, due to LMNA pathogenic variants, is the most frequent form of lipodystrophy in patients referred to our reference center, representing 23% of our recruitment, followed by other forms of FPLDs (20%)." (PMID 38678257, 2024). "In rare Mendelian lipodystrophies – as occurs in individuals who harbor pathogenic LMNA mutations – an extreme example of this paradigm leads to marked reduction of ASAT and GFAT but increased VAT and increased rates of severe insulin resistance." (PMID 36650173, 2023). "In atypical WS associated with the R133L mutation of the LMNA gene, the severity of metabolic complications is positively related to the degree of lipodystrophy." (PMID 35281936, 2022). "In the human disease spectrum, hundreds of mutations in the LMNA gene have been identified and are associated with more than a dozen human diseases, especially including lipodystrophy." (PMID 35281936, 2022). "Mutations in the LMNA gene, besides causing lipodystrophy, lead to a wide spectrum of tissue-specific disorders." (PMID 35384599, 2022). "Mutations in the LMNA gene, which codes for the lamin A/C proteins, cause a variety of diseases including premature aging, muscular dystrophy, lipodystrophy, and bone abnormities." (PMID 34246298, 2021). "The lipodystrophy and cardiac phenotypes seen in this family were highly suggestive of a possible LMNA mutation while ALS mutations also needed to be examined." (PMID 33661429, 2021). "Muscle functional defects are observed in some patients with lipodystrophy due to pathogenic variants in LMNA, CAVIN1, or PSMB8, among other genes." (PMID 35046902, 2021). "Mutations in the LMNA gene resulted in lipodystrophy, which directly affected lipid metabolism and storage in clinical." (PMID 30705772, 2019). "We were not able to search for mutations in other candidate genes for lipodystrophy, such as LMNA, but this genetic testing represents a future project." (PMID 30622652, 2019). "Several LMNA mutations, either leading to a lipodystrophy or associated with signs of premature ageing, also triggered vascular smooth muscle cell senescence with osteoblastic transdifferentiation and calcification." (PMID 30901896, 2019). "Our previous study linked LMNA variant p.G602S to type 2 diabetes and showed that ∼0.3% of African Americans carry this allele, and revealed a dominant lipodystrophy-causing variant (p.I299V) in 0.347% of Latinx individuals in ExAC." (PMID 31024910, 2019). "To date, these findings have been limited to a few muscular dystrophy and lipodystrophy LMNA mutations but seem shared with a distinct nuclear envelope disease, emerin-deficient muscular dystrophy." (PMID 29750601, 2018). "The importance of these structures is now unquestioned given the wide range of degenerative diseases that stem from LMNA gene mutations, including muscular dystrophy disorders, peripheral neuropathies, lipodystrophies, and premature aging syndromes." (PMID 29637811, 2018).